CD4 (CD4 molecule)
Diseases named in the same sentence as CD4 in open-access papers (continued):
Sharing a sentence is not in itself a finding about the gene and the disease.
tumor (continued). "To further confirm above observations, we sorted and performed scRNA‐seq analysis on single positive T (SPT) cells, including 3676 tumor‐associated CD4+T cells and 4470 CD8+T cells." (PMID 32670760, 2020). "To understand BGRDs beyond the CD4+ T cell, we defined 6262 and 8409 genes with BGRDs in at least one of 113 and 117 H3K27me3 ChIP-Seq datasets of non-tumor samples from the ENCODE31 and Roadmap Epigenomics Project32, respectively." (PMID 33144558, 2020). "CD4 memory resting T cells, M0 macrophages, and M2 macrophages were the most common tumor-infiltrating immune cells in both high- and low-risk patients." (PMID 33194633, 2020). "We have also demonstrated that tumor cells highly upregulate the expression of IDO which causes apoptosis of both CD4 and CD8 T cells." (PMID 32582152, 2020). "Specifically, the cytotoxic properties of CD8+ T cells make them the main cells associated with the control of immunogenic tumor cell growth, whereas CD4+ T cells function primarily by secreting various cytokines." (PMID 33584797, 2020). "To search for putative tumor-associated antigens in the early transformation phase, we similarly activated purified normal CD4+ T cells via CD3/CD28 beads and transduced them with lentiviral vector expressing NA or KD." (PMID 33348781, 2020). "This is mediated by reduced T-box expressed in T cells (T-bet) and increased forkhead box protein P3 FoxP3 expression in tumor-associated CD4+ T cells." (PMID 33086598, 2020). "CD4+ regulatory T cells possess immune functions that are associated with tumor cell immunosuppressive process." (PMID 32265690, 2020). "In particular, CD4 TH1 cells characterized by the secretion of IFNγ (Interferon gamma)-associated cytokines can not only contribute to direct tumor cell killing but also endow CD8 T and NK (natural killer) cells with optimal cytotoxic functions." (PMID 32707692, 2020). "While tumor resident CD4+ T cells were more activated, a significant proportion highly expressed Treg-associated genes at the tumor." (PMID 32433953, 2020). "CHI3L1 signaling plays a critical role in cancer cell growth, proliferation, invasion, metastasis, angiogenesis, activation of tumor-associated macrophages, and Th2 polarization of CD4+ T cells." (PMID 32929074, 2020). "CD4+ tumor-associated lymphocytes express CCL5, and coculture with GC cells further increases CCL5 secretion by CD4+ T cells." (PMID 32630699, 2020). "In HCC patients, high levels of tumor-infiltrating CD4+ T lymphocytes are associated with a low recurrence rate and a reasonable prognosis." (PMID 32742442, 2020). "Attenuated bacterial antigens play an important role in immunotherapy as they regulate various immune cells such as tumor-associated macrophages, dendritic cells, tumor-associated lymphoid cells such as NK cells, CD4+, and CD8+ cells and regulatory T cells." (PMID 32547541, 2020). "The CD4-GZMA cell specific genes were enriched in pathways associated with tumor metabolism and malignant progression." (PMID 33043022, 2020). "In BRAC tissues, the expression of HSP90AA1, HSP90AB1, and HSP90B1 was conformably correlated with the expression of biomarkers of some lineages of CD4+ helper T (Th) cells and tumor-associated macrophages (TAMs)." (PMID 33145341, 2020). "Tumor-associated stromal cells include cancer-associated fibroblasts, regulatory T cells, CD4+ helper T and CD8+ cytotoxic T cells, tumor-associated macrophages, and myeloid-derived suppressor cells." (PMID 33287297, 2020). "Meanwhile, CD4+ memory T cells are associated with tumor cell metastasis to lymph nodes and tumor progression." (PMID 32850314, 2020). "The evaluation of tumor‐infiltrating CD4 T cells has revealed that locally expressed MHC class II tumor‐associated antigen showed gain of function to eliminate tumor cells in the microenvironment." (PMID 32237049, 2020).
tumor (continued). "It is well known that tumor associated macrophages were negatively correlated with clinical outcome and B cell, CD4+ T cell, CD8+ cell, neutrophil cell, and dendritic cell were positively correlated with prognosis." (PMID 33520701, 2020). "Several studies showed that CXCL9 and CXCL10, particularly CXCL10 produced by tumor or host cells can recruit CXCR3+ tumor-infiltrating CD4+ T cells, CD8+ T cells and NK cells that are associated with tumor suppression." (PMID 32547545, 2020). "Blimp-1-deficient CD4+ T cells showed reduced tumor control compared to WT CD4+ T cells, supporting the relevance of Blimp-1 in CD4-mediated tumor control." (PMID 31924474, 2020). "Downregulation or loss of MHC class I reduces tumor immunogenicity, decreases the percentage of CD8 and CD4 tumor infiltrating lymphocytes (TILs) and causes resistance to immunotherapy, which correlates to poor prognosis and patient survival." (PMID 32162275, 2020). "In particular, IFN-γ secretion by activated CD8+ (and CD4+) T-cells has long been associated with effective tumor recognition and used as a functional readout to detect tumor-reactive T-cells." (PMID 32695101, 2020). "Among the Eph receptor family members, EphA2 and EphA3 have been identified as tumor-associated antigens (TAAs), and their epitopes can be recognized by both CD4+ and CD8+ T cells." (PMID 33288738, 2020). "By transferring different numbers of tumor-associated self-Ag-specific TCR transgenic CD4 T cells, Malandro and co-authors showed that initial precursor frequency inversely correlated with in vivo expansion and functional outcomes." (PMID 32973794, 2020). "Targeting CCR2+ TAM and CXCR2+ TAN in combination caused influx of both CD8+ and CD4+ T cells in the tumor microenvironment, improving antitumor immunity and reducing tumor burden." (PMID 31297636, 2020). "PitNETs with more CD4+ T cells had higher microvessel area, while tumours with more FOXP3+ cells were associated with lower microvessel density." (PMID 32946040, 2020). "Successful outcomes following immunotherapies for the treatment of cancer have been linked to the generation of effector CD8+ and CD4+ T-cell responses, followed by the establishment of memory T-cell population capable of combatting re-emergence of the tumor." (PMID 33002018, 2020). "In conclusion, a high CD8 T cell score is associated with better survival in TNBC, particularly when tumor CD4 memory T cells were elevated." (PMID 32971948, 2020). "Because cytokine exposure in vitro can encourage growth of different T cell polarizations, we validated that the cultured CD4+ phenotypes were associated with tumor rejection." (PMID 33362774, 2020). "Tumor control was associated with increased levels of activated CD8+ and CD4+ T found in lymph nodes, spleen, and tumor infiltrates." (PMID 33266109, 2020). "High levels of CX3CL1 is known to be associated with an increased number of CD8+ and CD4+tumor infiltrating lymphocytes (TILs) in colorectal cancer and is a good prognostic indicator of survival." (PMID 32896273, 2020). "It was reported that B16 tumor growth in C3aR deficient mice was suppressed by relieving the neutrophil and CD4+ T cell responses." (PMID 31931851, 2020). "Other CD4 T helper subpopulations including Th2 and Th17 have been generally associated with tumor progression." (PMID 33329566, 2020). "The CXCR4 expression level was found to be significantly associated with tumor purity and positively correlated with the infiltration of B-cells, CD4+ T-cells, CD8+ T-cells, macrophages, neutrophils, and dendritic cells." (PMID 33194726, 2020). "It is interesting to note that the enrichment of CD3 in tumour regions was associated with improved OS in this study, independently of CD4 T helper cells and cytotoxic CD8 T lymphocytes." (PMID 33261133, 2020).
tumor (continued). "Higher risk scores were correlated with increasing values for tumor-infiltrating immune cells, which included B-cells, CD4+ T-cells, CD8+ T-cells, neutrophils, macrophages, and dendritic cells (all P < 0.05)." (PMID 32508884, 2020). "For example, T helper type 1 (Th1) CD4+ T cells, M1-like tumor-associated macrophages (TAMs), and eosinophils each enhance tumor vessel normalization." (PMID 32759497, 2020). "Subsequently, however, it became apparent that IFN-γ secreted by Th1 CD4 T cells causes the upregulation of MHC-II molecules on the surface of tumor cells, enabling MHC II-restricted killing." (PMID 32630460, 2020). "The immune cells analyzed in HCC tissues included CD8+ T cells, CD4+ T cells, B cells, tumor-associated macrophages (TAMs), monocytes, M1 and M2 macrophages, neutrophils, DCs, and natural killer (NK) cells." (PMID 31927532, 2020). "These tumor-associated neutrophils (TANs) have the potential to suppress the anti-tumor activities of tumor-specific infiltrating lymphocytes (TILs) of the CD4+ Th1 and cytotoxic CD8+ phenotypes, as well as driving angiogenesis and metastasis." (PMID 32244751, 2020). "Increase in CD4+CD25+/total CD4+ ratio among tumor-bearing individuals was associated with tumor advancement and suggestive of a more suppressive functionality in the immune systems of this group of tumor-bearing mice treated with the protein." (PMID 32306719, 2020). "Direct stimulation of NK, CD8+ and CD4+ T cells by IL-33 has been reported to promote Th1-associated anti-tumor responses in several tumor models." (PMID 33329534, 2020). "Intratumoral CD4+ Th2 cells and regulatory T cells (Tregs) are associated with reduced survival, whereas cytotoxic CD8+ T cells and CD4+ Th1 cells mediate tumor protection and are associated with prolonged survival in PDAC." (PMID 32865617, 2020). "Various studies have confirmed the association of high densities of tumour-infiltrating not only CD11c+ or/and OX-62+ DCs but CD4+ or/and CD8+ T cells with a better overall survival." (PMID 32541941, 2020). "The low dose of anti-angiogenic treatment promotes the polarization of tumor-inhibitory M1-like tumor-associated macrophages and the infiltration of CD4+ and CD8+ T cells." (PMID 31695774, 2019). "In a study of lung adenocarcinoma, EMT markers were associated with enhanced tumor infiltration of CD4+Foxp3+ Tregs and upregulation of inhibitory immune checkpoint molecules such as programmed cell death (PD)-ligand (L) 1, PD-L2, TIM-3, B7-H3, and CTLA-4." (PMID 31096701, 2019). "Its expression in tumor-associated macrophages is a potential facilitator of NSCLC development by inhibiting CD4+ and CD8+ T-cell proliferation and cytokine production." (PMID 31337155, 2019). "Correlative data were also stratified by tumor type and the trends were maintained for all of the seven parameters that significantly associated with clinical response except for fold-change in CD4 T cells in the blood from baseline to cycle three." (PMID 30867072, 2019). "High infiltration of the tumor CD4+ T cells was associated with lower clinical stage at diagnosis (P = 0.006)." (PMID 31429521, 2019). "To identify the signaling pathways specifically activated on cancer-associated UTCαβ, we compared the transcriptome of tumor-associated Csf3r+/+ UTCαβ with γδ T cells and conventional CD4+ and CD8+ T cells and found 190 differentially expressed genes." (PMID 31257026, 2019). "This lower frequency found in metastatic patients compared with localised ones and in healthy subjects (45%) suggested that tumour progression is associated with a defect of pre-existing anti-TERT CD4+ Th1 immunity." (PMID 31358938, 2019). "In agreement with previous reports, systemic DNCB induced a mild inhibitory effect on tumor growth, associated with an increase in CD4+ and CD8+ T-cell levels in the tumor infiltrates, without significant changes in these population in the spleen." (PMID 31695610, 2019).
tumor (continued). "Their findings demonstrated that CD4+FoxP3+ Tregs and tumor-associated macrophages (TAM) were predominantly found at the initial (preinvasive) stage of PDA." (PMID 31652904, 2019). "It is well demonstrated that tumor‐infiltrating CD4 + T cells, which are able to recognize cancer associated antigens, are generated to become Th1 cells and stimulate M1‐macrophages via interleukin‐12 or IFN‐γ production." (PMID 31631566, 2019). "In contrast, the presence of Treg (CD4+CD25+FOXP3+T cells), a subset of CD4+ T cells, appears to cause tumor immunosuppression, especially in most solid tumors." (PMID 31118034, 2019). "T-reg-mediated immunosuppression causes a relevant reduction of CD8+ and CD4+ functionality in the tumor stroma and can recruit myeloid-derived suppressor cells." (PMID 31500143, 2019). "Tumor‐associated macrophages release a number of cytokines, chemokines, and enzymes that suppress the effector function of CD4+ and CD8+ T cells." (PMID 31365790, 2019). "K562-derived AAPCs have also been used to stimulate CD4+ T cells against Survivin, a tumor associated antigen (TAA)." (PMID 31156634, 2019). "Conversely, NFAT1 deficiency blunted the induction of anergy in tumor antigen-specific CD4+ T cells, thus enhancing anti-tumor responses." (PMID 31216652, 2019). "The increased CD3+CD4+T can directly kill tumors, and these cells can cause the release of interferons and perforin to accelerate the destruction of tumor cells." (PMID 31256187, 2019). "Comparing scRNA-seq profiles of tumor-associated T cells to our dataset reveals predominant activated CD8+ compared to CD4+ T cell states within multiple tumor types." (PMID 31624246, 2019). "Flow cytometry confirmed that enhanced Cd4 gene expression in JA-2042 was actually associated with enhanced CD4+ T cell infiltration by various tumor-infiltrating leukocytes." (PMID 30791458, 2019). "The proportion of tumor-associated CD4+ and CD8+ T cells as a percentage of all immune cells from B16 tumors isolated from miR-301a−/− mice was higher than those from WT mice." (PMID 31122259, 2019). "Nrp-1 deficiency on murine FoxP3+ CD4+ Treg cells has been reported to delay tumour growth correlated with enhanced activation of tumour-infiltrating CD8+ T cells." (PMID 31350404, 2019). "CD4+ helper T cells producing IL-9 (Th9) have been implicated in anti-tumor immunity, with Th9 differentiation inducible in vitro via IL-4 and TGFβ treatment." (PMID 30914642, 2019). "Tumor-associated inf-DC from mice developing lung carcinoma actively inhibit CD4+ and CD8+ T cell responses by releasing nitric oxide, a reactive radical with known T cell suppressive activities." (PMID 30979057, 2019). "Previous studies have demonstrated that tumor regression induced by IL12 administration in association with IFN-γ which can affect CD4 and CD8 T cell function." (PMID 31921693, 2019). "In support of this conclusion, Hepa1-6 tumors in chemerin-/- mice displayed increased proportions of MDSCs, tumor-associated macrophages (TAMs) and decreased IFNγ-expressing T-helper CD4+ and cytotoxic CD8+ T cells compared to Hepa1-6 tumors in wild-type mice." (PMID 31561459, 2019). "PD-1 + CD4 + T cells, together with tumor-associated macrophages (TAMs) are located in close proximity to HRS cells, comprising a unique niche in cHL8." (PMID 30783096, 2019). "In the NLR-CRP-low group, the CD8+ sTIL and CD4+ sTIL densities were significantly associated with tumor regression (P=0.043 and P=0.032, respectively)." (PMID 30867256, 2019). "Whole-cell vaccination, a promising strategy in immunotherapy, provides multiple identified and unidentified tumor-associated antigens (TAAs) that activate CD4+ and CD8+ CTLs, thereby minimizing immune escape." (PMID 31467912, 2019). "While individual treatments were ineffective, combination therapy markedly reduced tumor growth, blocked tumor cell proliferation, reduced tumor-associated macrophages, and increased CD4+ T cells." (PMID 31903163, 2019).
tumor (continued). "IHC staining showed that the numbers of tumor associated PD-1+ cells as well as CD4+ and CD8+ cells were significantly increased after exposure to NTHi for four weeks in an IL-17C-independent manner." (PMID 31316109, 2019). "CD4+ T cells (also known as helper T cells) recognize the tumour-associated antigens on the surface of antigen-presenting cells (e.g., dendritic cells, DC) and release cytokines that have a role on the regulation of the adaptive immunity." (PMID 31906092, 2019). "Some reports have associated the accumulation of CD4+FOXP3+CD25hi Tregs with poor prognosis owing to the suppression of anti-tumor immune response, and altered Treg number and function has been reported in patients receiving conventional or immune therapies." (PMID 31775882, 2019). "While transient CD4+ lymphodepletion remains a valid concern together with the “on-target off-tumor” toxicities associated with immunotherapy." (PMID 31413761, 2019). "Selected tumor-associated antigens (TAA) were effectively presented by MHC-II molecules to CD4+ T cells." (PMID 31212865, 2019). "IL-17 is a cytokine produced by an activated human memory CD4 T-cell Two cervical cell lines transfected with a cDNA encoding IL-17 exhibited a significant increase in tumor size." (PMID 31284453, 2019). "Depletion of CD4+ T cells led not only to the loss of anti-tumor effects mediated by the combination therapy with class II HER2-DC1 and anti-PD-1 but also to more rapid tumor growth and diminished survival." (PMID 31475002, 2019). "In univariate analysis, TNM stage, tumor location, and increased CD4+ T-cell ratio were associated with PFS." (PMID 30828566, 2019). "By contrast, tumor-associated CD4+ T cells projected mostly onto resting blood and tissue T cells, while CD4+ T cell activation states and associated markers (NME1, IFIT3) were largely absent." (PMID 31624246, 2019). "In the current study, results calculated by algorithms indicated that CD4+ T lymphocyte infiltration was significantly downregulated in high-risk tumor tissues and was associated with poor prognosis." (PMID 31612115, 2019). "In the same study, the authors showed that the antitumor effects of C3aR inhibition are linked with a decrease in tumor-associated macrophages and an increase in tumor-infiltrating neutrophils and CD4+ T lymphocytes." (PMID 31134065, 2019). "As NUP214-specific CD4+ T-cell responses was detected in the tumor from Pt #19, we reasoned that the mutated NUP214 epitope was naturally presented in the tumor microenvironment." (PMID 31221207, 2019). "Accordingly, the myeloid cell's Trim24 deficiency impaired the tumor infiltration of IFNγ-producing CD4+ and CD8+ effector T cells, suggesting that Trim24 deficiency impaired antitumor immunity through suppressed Stat6 acetylation in TAMs." (PMID 31554795, 2019). "Tumor-infiltrating CD4+ and CD8+ T-cells are associated with varying clinical outcomes and survival in many types of cancer such as colorectal, breast and lung cancers." (PMID 31480382, 2019). "IHC staining showed that numbers of tumor-associated CD4+ cells were reduced in anti-PD-1 treated Kras and Il-17c−/−/Kras mice." (PMID 31316109, 2019). "ICOS positive CD4+ cells and tumor-associated Treg can be activated by ICOSL-expressed plasmacytoid DCs." (PMID 31143539, 2019). "Tumor growth in WT mice was associated with increased tumor infiltrating CD4+ Treg cells that was further enhanced by treating mice with recombinant TRAIL, which also enhanced tumor growth." (PMID 31333662, 2019). "The CD4+ TCR Vβ9+ TIL clone that recognises the K7N7A8 mutated peptide GLLRYWRTERLF produced a cytotoxic T-cell response against the autologous tumour cell line, which was assessed in a standard CD107a induction assay." (PMID 30377343, 2019). "As a hallmark of cancer, tumor cells employ mechanisms of immune evasion to avoid elimination by protective CD4+ and CD8+ T cells." (PMID 31602007, 2019).